CCL21 (C-C motif chemokine ligand 21)
Diseases named in the same sentence as CCL21 in open-access papers (continued):
Sharing a sentence is not in itself a finding about the gene and the disease.
lung carcinoma (continued). "Towards achieving this goal, we are evaluating a non-DC based approach which utilizes vault nanoparticles for intratumoral CCL21 delivery for the purpose of initiating antitumor immune responses in lung cancer." (PMID 21559281, 2011). "In preclinical studies we demonstrated that intratumoral administration of CCL21 gene modified DC led to tumor eradication in murine lung cancer models." (PMID 21559281, 2011). "We are evaluating a non-DC based approach which utilizes vault nanoparticles for intratumoral CCL21 delivery to mediate antitumor activity in lung cancer." (PMID 21559281, 2011). "Based on this concept, we have previously shown that intratumoral administration of recombinant CCL21 reduces tumor burden in murine lung cancer models." (PMID 21559281, 2011). "We have previously shown that intratumoral recombinant CCL21 or CCL21 gene modified DC induce a T cell dependent tumor reduction in murine models of lung cancer." (PMID 21559281, 2011). "Based on our in vitro findings, CCL21-vaults were evaluated in a therapeutic lung cancer model in vivo." (PMID 21559281, 2011). "Previous results from our laboratory indicated that CCR7 and its ligand CCL21 regulate migration and invasion of lung cancer cells through the ERK1/2 pathway under hypoxic conditions and promote metastasis of lung cancer." (PMID 20569443, 2010). "In the clinical trial, we expect a maximum delay of two hours prior to intratumoral administration of our final product (CCL21-DC) into the patient's primary lung cancer due to the required safety testing to fulfill lot release criteria." (PMID 18644162, 2008). "Thus, CD93 in pMCs is also probably involved in the regulation of T-cell responses in lung cancer patients by promoting CCL21-mediated DC recruitment." (PMID 38250037, 2024). "When determining the concentrations of CCL21, CD11c+ DCs and EV miR-5193 in MPEs from lung cancer patients, we found that the EV miR-5193 concentration was positively correlated with the CCL21 and DC concentrations and the CCL21 and DC concentrations were positively correlated." (PMID 38250037, 2024). "In preclinical mouse models, CCL21 was shown to facilitate antitumor activity via recruiting and colocalizing NK cells, DCs, and T cells in tumors, and it was supported that anti-PD-1 administered in combination with CCL21-DC tumor antigen therapeutic vaccines eradicated lung cancer." (PMID 38067341, 2023). "In addition, toxicity of commercial CCL21 on MCF7 cells was similar to CCL21/IL1β recombinant protein, which is the anticancer antigen used for lung cancer treatment." (PMID 36037155, 2022). "Indeed, VEGF-C-overexpressing gliomas and metastatic brain tumors from lung cancer were more sensitive to RT than control tumors, very likely mediated through CCL21-dependent DC trafficking and CD8+ T cell activation." (PMID 35301438, 2022). "Moreover, several studies have indicated that CCR7-CCL19/CCL21 has an antitumor function by recruiting T lymphocytes and dendritic cells in lung cancer and other malignant tumors 44, 45, and few have been reported in HCC yet." (PMID 35673582, 2022). "In lung cancer, autologous DCs transduced with an adenoviral vector modified with the CCL21 gene significantly reduced the tumor load and T cell infiltration, accompanied by enhanced expression of IFN-γ, IL-12, and CXCL10, as well as molecules related to reduced immunosuppression in the TME." (PMID 34394083, 2021). "From a clinical perspective, a project aimed at exploiting vaults packaged with CCL21-INT for lung cancer therapy is currently in phase I, whereas MVP immunohistochemistry makes is possible to reliably identify potential markers of malignancy in uterine smooth muscle tumors." (PMID 33572350, 2021). "The anti-tumor efficacy of CCL21 was further confirmed in a transgenic murine model of lung cancer." (PMID 24810425, 2014).
lung carcinoma (continued). "We examined whether HS produced into CM of hLEC is required for binding of CCL21 to its receptor on lung carcinoma cells exposed to the medium." (PMID 21172016, 2010). "In addition, TNF-α could activate NF-κB pathway in LECs to promote their secretion of CCL21 and promote metastasis and invasion of lung cancer cells through the CCR7-CCL21 axis." (PMID 38566083, 2024). "For instance, a search for chemokine/chemokine receptor system in lung cancer showed that the interaction of CC-chemokine ligand 21 (CCL21) with its receptor CC-chemokine receptor 7 (CCR7) may help protect against tumor cell apoptosis through p-ERK-mediated increase of the Bcl-2/Bax ratio." (PMID 38031087, 2023). "In addition, the reports showed that the interaction of CCR7 and CCL21 is involved in various physiological processes including the proliferation and metastasis of different types of tumor cells, including breast, pancreatic and lung cancer." (PMID 33158173, 2020). "PD-1 blockade plus CCL21-DC tumor lysate vaccine therapy could benefit lung cancer patients." (PMID 32570793, 2020). "However, since no single mouse cancer model recapitulates all the key aspects of human disease, evaluation of CCL21-DC tumor Ag vaccine in combination with PD-1 blockade therapy in several lung cancer models will provide information on the general efficacy of the approach." (PMID 32570793, 2020). "CCL21 promotes the infiltration of T cells and dendritic cells into tumors, thereby enhancing immune activity, and the synergistic tumor-suppressive effects of the combination of CCL21 and ICI in lung cancer and pancreatic cancer mouse models." (PMID 38026978, 2023). "Cochrane’s Q test did not provide evidence of heterogeneity between CCL14 (p = 0.916), CCL19 (p = 0.446), CCL20 (p = 0.130), CCL21 (p = 0.878), CCL27 (p = 0.762), CXCL9 (p = 0.340) and CXCL13 (p = 0.770) and lung cancer." (PMID 38075694, 2023). "The intratumoral injection of CCL21 gene-modified DCs were found to facilitate eliciting systemic tumor-specific immune responses and tumor-infiltrating CD8+ T cells in lung cancer." (PMID 34122408, 2021). "In lung cancer, CCL21/CCR7 triggers tumor cell migration and invasion via the EMT and ERK1/2 signaling pathway, thus providing a potential target for lung cancer treatment." (PMID 33146700, 2020). "The study of CCL21/CCR7 will have important significance for the prevention and treatment of lung cancer metastasis." (PMID 33158173, 2020). "CCL1, CCL21, IP-10, CCL8 and CXCL9 levels were much higher in pleural effusions from patients with TP compared with lung cancer patients." (PMID 23028695, 2012). "Serum CCL21 levels are elevated in COPD patients and may contribute to the development of lung cancer." (PMID 37410739, 2023).
pancreatic cancer (22 papers, 2014 to 2025). "In this study, we transduced CCR7-positive PANC-1 cells with lentiviral vector expressing human CCL21 (hCCL21) to determine if CCL21 affects expression of certain genes associated with pancreatic cancer formation and development." (PMID 29687228, 2020). "The levels of CXCL10 and CCL21 were associated with pain in pancreatic cancer patients." (PMID 35468838, 2022). "However, the molecular mechanisms or signaling pathways underlying CCL21-induced chemotaxis in cancer, especially in pancreatic cancer, remain largely unknown." (PMID 29687228, 2020). "Markedly upregulated expression of CCR7 was observed in patients suffered with pancreatic cancer, contributing to the enhancement of angiogenesis via chemotactically binding with CCL21." (PMID 38361743, 2024). "For instance, by influencing the EMT pathway, CCL21/CCR7 facilitated the spread of pancreatic cancer cells." (PMID 36829431, 2023). "The results suggested that CCL21 promotion of pancreatic cancer cell growth towards sensory neurons was important for pain development." (PMID 35203305, 2022). "CCR7 expression is significantly increased in patients with pancreatic cancer and induces intra-tumor angiogenesis and lymphangiogenesis through chemotactic interactions with its ligand, CCL21." (PMID 36312035, 2022). "Recently, CXCL10 and CCL21 are demonstrated to promote migration of pancreatic cancer cells toward sensory neurons and increase the frequency of cancer-associated pain." (PMID 33681290, 2021). "Previous studies have revealed that up-regulation of CCL21 is a favorable prognostic factor in pancreatic cancer, renal cell carcinoma, colorectal cancer and BC, and represents a negative prognostic factor in bladder cancer and gastric cancer." (PMID 33146700, 2020). "CCL21 regulates pancreatic cancer immunity possibly through governing the expression of a panel of tumor-associated genes, including MMP-9." (PMID 29687228, 2020). "Based on these data, CCL21 seems to have both anti- and pro-tumor effects on pancreatic cancer cells." (PMID 29687228, 2020). "Another possible reason is that the in vitro experimental environment in this study differs from the in vivo tumor microenvironment where pancreatic cancer cells reside, leading to inadequate responses of CCL21 to microenvironmental cues." (PMID 29687228, 2020). "Some genes, including matrix metallopeptidase-9 (MMP-9), were identified, providing new insight into CCL21 function in pancreatic cancer." (PMID 29687228, 2020). "Our study found that the expression level of LYVE-1 increased in pancreatic cancer stem cells after treatment with CCL21, which supply the direct molecular mechanism that CCL21 was responsible for mediating lymph node metastasis." (PMID 27505247, 2016). "The results of the present study detected high levels of CCL21/CCR7 in pancreatic carcinoma tissues and metastasis lymph nodes." (PMID 27505247, 2016). "Similar variation patterns were also observed for CCR7 and CCL21 in pancreatic cancer, for CCL21 in squamous cell carcinoma or for CCR7 and VEGF-C in pancreatic ductal adenocarcinoma." (PMID 25744065, 2015). "CCL21 injection into pancreatic tumors has been shown to be beneficial by inhibiting tumor growth, decreasing the size of distant metastasis, increasing T cell infiltrate and even enhancing antigen cross-presentation by DC." (PMID 24762633, 2014). "Of the same family, CCR7 combined with its ligand CCL21 was recently reported to synergistically guide pancreatic cancer cells toward lymphatic vessels and promote lymph node metastasis." (PMID 24587996, 2014). "And the expression of CCR7 and its ligands CCL19/CCL21 in human pancreatic cancer tissue had an obvious correlation with the high rate of lymphatic metastasis." (PMID 24587996, 2014). "CCL21 administered intratumorally has even been sufficient to establish TLS within pancreatic cancers." (PMID 24762633, 2014).
pancreatic cancer (continued). "A study in pancreatic cancer reported that CCL21 could enhance T cell-mediated cytotoxicity and the efficacy of ICIs." (PMID 38367070, 2024). "elucidated that intratumoral injection of CXCL13 and CCL21 could induce TLSs formation in the orthotopic model of pancreatic tumor, resulting in a better therapeutic effect of gemcitabine." (PMID 36420257, 2022). "In contrast, the CCL21/CCR7 axis signal also plays an important role in pancreatic cancer." (PMID 34948416, 2021). "Various lines of evidence also support the dual roles of CCL21 in pancreatic cancer development." (PMID 29687228, 2020). "The correlation between CCL21 and MMP-9 in PANC-1 cells may provide valuable insights into molecular mechanisms underlying the functions of CCL21 in pancreatic cancer." (PMID 29687228, 2020). "Therefore, targeting CCL21 is a potential therapeutic intervention in cancers, including pancreatic cancer." (PMID 29687228, 2020). "Our data indicate that CCL21 does not suppress pancreatic cancer cell migration; however, the DNA microarray data demonstrate that CCL21 can regulate expression of certain tumor-associated genes." (PMID 29687228, 2020). "Consequently, the role of CCL21 in pancreatic cancer cell migration and metastasis needs to be reassessed in an in vivo study, which requires further investigation." (PMID 29687228, 2020). "To determine if pancreatic cancer stem-like cells were a suitable model for CCR7-mediated potentiality of CCL21-driven pancreatic carcinoma metastasis, we evaluated chemokine receptor expression levels in total, CD133+, and CD133− pancreatic cancer cells by RT-qPCR." (PMID 27505247, 2016). "We examined the ability of CCL21/CCR7 to promote CD133+ pancreatic cancer stem-like cells survival." (PMID 27505247, 2016). "We tested the hypothesis that CCL21/CCR7 increases the migration potentiality of pancreatic cancer stem-like cells as well as promoting survival, by CCR7 knockdown with small interfering (si) RNA." (PMID 27505247, 2016). "This apparent contradiction between receptor and ligand expression related to vessel density localized to the pancreatic cancer, such that CCL21 expression was linked to microvessel density but not microlymphatic vessel density, whereas for CCR7 expression, effects were reversed." (PMID 35203305, 2022). "In pancreatic cancer, co-injecting CXCL13 and CCL21 into the tumors of a murine model drove TLS neogenesis and markedly enhanced the anti-tumor effects of chemotherapy." (PMID 41457151, 2025). "CCR7/CCL21 promoted survival and metastasis of the CD133+ pancreatic cancer cells via modulation of the ERK/NF-κB pathway." (PMID 35203305, 2022). "Our results suggest that Fx suppresses the CCL21/CCR7 axis downstream of Rho signaling, BTLA, TME, EMT, and adhesion in pancreatic tumors in mice." (PMID 34948416, 2021). "There is little information on the CCL21/CCR7 axis, BTLA, TME, EMT, and adhesion signals on the effect of natural compounds on pancreatic cancer." (PMID 34948416, 2021). "Consistent with previous findings, our data indicate that endogenous expression of CCL21 is undetectable in PANC-1 cells, suggesting a possible protective role of CCL21 in pancreatic cancer cells." (PMID 29687228, 2020). "CCL21/CCR7 promoted metastasis and survival of CD133+ pancreatic cancer stem-like cells and regulated CD133+ pancreatic cancer stem-like cells metastasis by modulating EMT and Erk/NF-κB pathway." (PMID 27505247, 2016). "The role of CCL21/CCR7 in mediating metastasis and survival of CD133+ pancreatic cancer stem-like cells was detected by Transwell assays and flow cytometry, respectively." (PMID 27505247, 2016). "This study investigated the role of CCL21/CCR7 in promoting EMT and metastasis of cluster of differentiation 133+ (CD133+) pancreatic cancer stem-like cells." (PMID 27505247, 2016). "We therefore evaluated the effect of CCL21/CCR7 on Erk and NF-κB activation in CD133+ pancreatic cancer stem-like cells." (PMID 27505247, 2016).
pancreatic cancer (continued). "CCL21 levels were low and CCR7 levels high in pancreatic cancer tissue compared to normal pancreas." (PMID 35203305, 2022). "Accumulating evidence suggests that over-expression of CCR7 is correlated with lymphatic invasion; CCL21/CCR7 regulated migration and metastasis in a variety of lung, esophageal, and pancreatic cancer cells, possibly allowing them to access the lymphatic system and spread to regional lymph nodes." (PMID 27505247, 2016). "To examine if there is a correlation between CCL21 and MMP-9, we performed Western blot analysis and demonstrated that CCL21 promoted MMP-9 protein expression in PANC-1 cells, suggesting that CCL21 plays a potential role in vasculogenesis and vascularization in pancreatic cancer." (PMID 29687228, 2020).
atherosclerosis (21 papers, 2010 to 2025). A disease characterized by the build-up of fatty material and calcium deposition in the arterial wall resulting in partial or complete occlusion of the arterial lumen. "The logistic analysis revealed that sVCAM-1 (on day 7) and CCL-21 (on day 7) were associated with the progression of atherosclerosis in MINOCA patients." (PMID 38138896, 2023). "In line with this, the CCR7/CCL19/CCL21 dyad has also been implicated in various disorders characterized by inflammation and matrix remodeling such as atherosclerosis, rheumatoid arthritis and inflammatory bowel disease." (PMID 25398010, 2014). "CCL21 is associated with inflammatory and vascular processes and its association to atherosclerosis has been previously defined." (PMID 21701687, 2011). "In an arterial graft transplantation model that induced atherosclerosis, the administration of neutralizing antibodies against CCL21 and CXCR3 suppressed TLS formation and prevented the progression of atherosclerosis." (PMID 41029827, 2025). "Increased levels of CCL19 and CCL21 in atherosclerosis can lead to changes in T-cell and macrophage responses by regulating dysfunction, thus reducing plaque stability and contributing to atherosclerosis development." (PMID 40535169, 2025). "Based on the signs of the regression coefficients, a direct relationship of sVCAM-1 and CCL-21 with the probability of atherosclerosis progression was established." (PMID 38138896, 2023). "According to the predictive model of binary logistic regression, factors associated with the progression of atherosclerosis in MINOCA patients included concentrations of sVCAM-1 (day 7) and CCL-21 (day 7)." (PMID 38138896, 2023). "The role of CCL19 and CCL21 in experimental atherosclerosis in mice is still disputed as results from different studies are contradictory." (PMID 33503867, 2021). "In order to investigate the role of CCR7/CCL19/CCL21 in atherosclerosis progression, the plaque-containing arterial segments from apo E-deficient mice were transplanted into the wild-type recipient normolipidemic mice to induce an atherosclerosis regression." (PMID 34345249, 2021). "Intranasal delivery of E-selectin prior to initiation of high-fat chow decreased atherosclerosis, serum total cholesterol, and expression of the leucocyte chemoattractant CCL21 that is typically upregulated in atherosclerotic lesions of ApoE−/− mice." (PMID 21701687, 2011). "CCL19 and CCL21 are expressed on macrophages and synovial fibroblasts and have also been reported to be elevated in the sera of patients with chronic inflammatory diseases, such as RA and atherosclerosis." (PMID 38711500, 2024). "The key factors that were associated with atherosclerosis progression in MINOCA patients are sVCAM-1 and CCL-21, which may suggest a complex genesis of atherosclerosis progression due to structurally altered plaques and changes in the microcirculatory bed." (PMID 38138896, 2023). "A clinical study demonstrated that CCL19 and CCL21 was up regulated in carotid atherosclerosis in 158 patients compared to a control of 20 patients, suggesting an important role for these chemokines in atherosclerosis." (PMID 33503867, 2021). "Hence, high CCL21 levels have been related to various inflammatory disorders like inflammatory bowel disease, rheumatoid arthritis and atherosclerosis." (PMID 23593305, 2013). "As well as being up-regulated in clinical and experimental atherosclerosis, CCL21 is also involved in neuroinflammation, suggesting how reductions in this chemokine secondary to intranasal E-selectin may also be beneficial in stroke." (PMID 21701687, 2011). "The key biomarkers that were associated with atherosclerosis progression in MINOCA patients are sVCAM-1 and CCL-21, which may suggest a complex genesis of atherosclerosis progression due to the structurally altered plaques and changes in the microcirculatory bed." (PMID 38138896, 2023).